INS (insulin)
Diseases named in the same sentence as INS in open-access papers (continued):
Sharing a sentence is not in itself a finding about the gene and the disease.
Hepatic steatosis (1,905 papers, 2003 to 2026). Steatosis is a term used to denote lipid accumulation within hepatocytes. "Among them, GLP-1 receptor agonists have shown efficacy in reducing hepatic steatosis, inflammation, and fibrosis-related biomarkers, primarily through weight loss and enhanced insulin sensitivity." (PMID 42195239, 2026). "Initial studies suggest that such therapies can improve insulin secretion, assist pancreatic beta cell preservation and enhance insulin-mediated glucose metabolism while reducing glucagon secretion and risk of fatty liver disease." (PMID 41174263, 2026). "This inverse relationship between SHBG and insulin is particularly pronounced among women with greater liver fat accumulation, suggesting a compounded metabolic risk in the presence of both hepatic steatosis and decreased SHBG." (PMID 41586225, 2025). "By modulating the gut microbiota, yogurt can mitigate the adverse effects of an HFD by leading to a healthier gut environment, improving insulin sensitivity, and reducing the risk of hepatic steatosis." (PMID 40507838, 2025). "In model 4, after continued adjustment for insulin, Hepatic steatosis, and HOMA-IR, the risk of GDM was reduced by 55% (95% CI: 0.19 to 0.97, p = 0.043)." (PMID 40880520, 2025). "The genetic variants most consistently associated with hepatic steatosis implicate genes involved in lipoprotein input or output, glucose metabolism, adiposity/fat distribution, insulin resistance, or mitochondrial/ER biology." (PMID 40166930, 2025). "Beyond its role in immunology, IL-15 is involved in muscle metabolism, contributing to fat loss, improved insulin sensitivity, and reduced hepatic steatosis." (PMID 41301428, 2025). "Its pathogenesis is complex and intricately linked to abnormal fat accumulation in the liver, i.e., hepatic steatosis, and systemic and hepatic insulin resistance." (PMID 40362294, 2025). "This phenomenon, known as “selective hepatic insulin resistance” or “selective insulin resistance and response”, causes hepatic steatosis." (PMID 41155548, 2025). "In general, it was observed that animals with overexpression of ERα in the liver showed protection against hepatic steatosis induced by a high-fat diet, associated with improved liver insulin sensitivity." (PMID 39846638, 2025). "Specifically, high intake of ultra‐processed foods and sugary drinks has been strongly associated with an increased risk of hepatic steatosis, insulin resistance and systemic inflammation, which contribute to liver disease progression." (PMID 40371883, 2025). "In the literature, LEAP-2 has been associated with hepatic steatosis, impacting the lipolytic/lipogenic pathway and insulin signaling in mice and humans." (PMID 41226108, 2025). "Semaglutide has been shown to ameliorate hepatic steatosis through weight loss, insulin sensitization, and direct reduction of hepatic fat content." (PMID 41020234, 2025). "GLP-1 analogue: Reduces hepatic steatosis via weight loss, improved insulin sensitivity, and direct hepatocyte effects (↓ lipogenesis, ↑ fatty acid oxidation)." (PMID 40951083, 2025). "Decreased levels of hsa-miR-488-3p and hsa-miR-148a-3p were linked to impaired glucose metabolism, insulin sensitivity, and hepatic lipid regulation, increasing the risk of hepatic steatosis." (PMID 40699679, 2025). "Other observed benefits include weight loss, improved insulin sensitivity, normalization of serum uric acid, and a reduction in hepatic steatosis—each with important metabolic implications." (PMID 41010553, 2025). "Excessive intake of these sugars, especially high-fructose corn syrup and sweetened beverages, is closely linked to hepatic steatosis, insulin resistance, and systemic inflammation." (PMID 40647314, 2025). "Clinical trials further demonstrate that EPA and DHA supplementation alleviates hepatic steatosis and inflammation while improving insulin sensitivity and reducing cardiovascular risk, key MASLD comorbidities." (PMID 40905021, 2025).
Hepatic steatosis (continued). "Glycemic control should be optimized using agents with hepatic benefits, particularly GLP-1 receptor agonists and SGLT2 inhibitors, which not only improve insulin sensitivity but also promote weight loss and reduce hepatic steatosis." (PMID 40734888, 2025). "Polymorphisms affecting insulin sensitivity, lipid metabolism, hepatic steatosis, and fibrosis progression have been shown to vary across racial groups." (PMID 41048829, 2025). "Elevated systemic UA levels are associated with impaired insulin signaling and exacerbated hepatic steatosis." (PMID 40398602, 2025). "The administration of 120 mg of orlistat three times daily with a hypocaloric diet for 16 weeks promoted weight loss in obese alcoholic fatty liver patients compared to the control, with significantly improved insulin sensitivity and liver enzymes." (PMID 40005380, 2025). "The patients achieved weight loss of 7.2% and 26.9%, reduced hepatic steatosis, and improved glycemic control, including an 83% reduction in insulin requirement in one case." (PMID 41312179, 2025). "Animal studies have demonstrated that TRF confers numerous benefits, including weight loss, obesity prevention, improved insulin sensitivity, reduced liver fat content, and prevention of hepatic steatosis and hyperlipidemia." (PMID 40410852, 2025). "HOMA-IR had been showed to be a good predictor for hepatic steatosis and fat content and insulin as a risk factor for MASLD." (PMID 39138826, 2025). "Conversely, in insulin-deficient conditions, such as in the lomitapide-treated patients with pancreatitis, hepatic steatosis remains mild despite reduced export." (PMID 40869061, 2025). "Improvement in insulin sensitivity in this cohort was associated with decreased hepatic steatosis and the amelioration of hepatic function." (PMID 41157142, 2025). "For instance, GPR55‐deficient mice show defective insulin signaling and a significant increase in liver fatty acid synthase, leading to hepatic steatosis." (PMID 39417398, 2024). "The two diets did not vary in terms of mean weight loss, but the Mediterranean diet significantly reduced liver steatosis and improved insulin sensitivity." (PMID 38891759, 2024). "Sexual dimorphism in adipose tissue distribution and substrate metabolism significantly affects insulin sensitivity and cardiometabolic health, both of which are strongly associated with hepatic steatosis and fibrosis." (PMID 39457270, 2024). "To explore the mechanism underlying improved hepatic steatosis and glycemic traits in Slc39a5-/- mice we evaluated two key signaling hubs that mediate lipid metabolism and insulin sensitivity, AMPK and AKT." (PMID 39671241, 2024). "The inverse association of FG in liver steatosis was inconsistent with the findings of liability to T2D, insulin, and glycemic signal class of HbA1c." (PMID 38926684, 2024). "A weight loss of 5% improves pancreatic β-cell function, insulin sensitivity, and hepatic steatosis." (PMID 39470335, 2024). "Specific dietary patterns, such as the Mediterranean diet, which is rich in fruits, vegetables, whole grains, and healthy fats, have been associated with reduced hepatic steatosis and improved insulin sensitivity in pediatric populations." (PMID 39337412, 2024). "During high-fat feeding, hepatic Bmal1 deficiency results in marked insulin resistance and liver steatosis." (PMID 39060446, 2024). "Visceral fat dysfunction is suggested as a major factor in causing and sustaining chronic inflammation, liver steatosis, and eventual systemic insulin resistance." (PMID 39347124, 2024). "Genetic liability to T2D and elevated fasting insulin (FI) likely increased risk of liver steatosis (ORliability to T2D: 1.14 per doubling in the prevalence, 95% CI: 1.10, 1.19; ORFI: 3.31 per log pmol/l, 95% CI: 1.92, 5.72) and related biomarkers." (PMID 38926684, 2024).
Hepatic steatosis (continued). "Metabolic dysfunction-associated fatty liver disease (MAFLD) defines fatty liver disease related to systemic metabolic dysregulation due to insulin resistance." (PMID 38662298, 2024). "These gut bacterial changes in C-HFD group had predicted associations with fatty liver disease and with lipogenic, inflammatory, glucose metabolic, and insulin signaling pathways." (PMID 38931284, 2024). "Another study used four-month-old mice with a hepatic PTEN deficiency and showed hepatic steatosis, increased insulin sensitivity, and glucose uptake with an increased de novo lipogenesis, glycolysis, and glucose infusion rate." (PMID 36670982, 2023). "Another study found a weak association between genetically instrumented hepatic steatosis and two glycemic traits: fasting glucose and fasting insulin." (PMID 37223039, 2023). "Phenylalanine and its derivative phenylacetic acid have been linked to hepatic steatosis by contributing to triglyceride accumulation and inhibiting insulin functions." (PMID 37759983, 2023). "Elevated fasting insulin concentrations seem to be a hallmark in hepatic steatosis, likely associated with the inverse association between hepatic TG content and insulin clearance by the liver." (PMID 37591342, 2023). "Oxidative stress is another mechanism associated with impaired insulin signalling, hepatic steatosis and adiposity." (PMID 38067134, 2023). "GLP-1 receptor signaling in hepatocytes revealed that exenatide alleviates hepatic steatosis by regulating hepatic insulin clearance through induction in mice, highlighting the fact that increased insulin clearance has been linked to the improvement of NAFLD." (PMID 37367037, 2023). "The repression of these genes and their association with hepatic glucose homeostasis, insulin sensitivity and increased serum triglycerides and hepatic steatosis have been the subjects of independent reports." (PMID 36674967, 2023). "Our data showed that PFOS exposure caused hepatic steatosis, as evidenced by significant increases in triglyceride levels, expression of ATP-citrate lyase, and fatty acid synthase, as well as fasting insulin levels." (PMID 38075064, 2023). "Chronic treatment of diet-induced obese mice with Rimo-NPs resulted in reduced hepatic steatosis and liver injury as well as enhanced insulin sensitivity, which were associated with enhanced cellular uptake of the formulation into hepatocytes." (PMID 36442615, 2023). "To investigate the underlying mechanism mediating improved hepatic steatosis and insulin sensitivity, we assessed the expression of downstream targets of FGFR4." (PMID 36586437, 2023). "In animal models, overexpression of ANGPTL6 is associated with increased energy expenditure, protection of hepatic steatosis, resistance to high-fat diet-induced overweight, and increased insulin sensitivity compared with controls." (PMID 37274345, 2023). "Hepatic PDK4 expression has been linked to impaired insulin sensitivity and fatty liver disease through stimulation of fatty acid uptake and synthesis in the liver." (PMID 36525084, 2023). "Characteristic metabolites associated with fatty liver disease and increased insulin and liver glycogen storage were identified." (PMID 38169827, 2023). "While its use has been somewhat questioned due to adverse event concerns, a more recently-developed agent, lobeglitazone, exhibits improved safety with improvements in insulin sensitivity and liver steatosis in T2D-associated NAFLD." (PMID 37396181, 2023). "Obese cats are predisposed to many metabolic dyscrasias, such as insulin resistance, altered blood lipids, and feline hepatic lipidosis." (PMID 36756310, 2023). "HFD-induced, increased hepatic lipogenesis is an important metabolic abnormality underlying the pathogenesis of hepatic steatosis in insulin-resistant livers." (PMID 35831885, 2022).
Hepatic steatosis (continued). "Treatment with brown algae crude extract can increase insulin sensitivity and decrease FFAs levels, reducing an individual’s risk of developing hepatic steatosis." (PMID 36364926, 2022). "Refined grains, a component of the “western” dietary pattern, not only increase the risk of hepatic steatosis but also cause insulin resistance along with other components of this pattern, such as foods with a high glycemic index." (PMID 35354433, 2022). "Reduced hepatic steatosis in RAPA‐treated type 2 diabetic rats has been observed in association with improved insulin sensitivity." (PMID 35986566, 2022). "At 10w of age, Nkcc1βKO mice showed reduced hepatic Insr expression/signaling, mild focal liver steatosis and reduced hepatic glycogen stores considered early metabolic manifestations of deficient insulin-mediated responses in vivo." (PMID 36580474, 2022). "The marked improvements in hepatic steatosis were associated with the decreases in plasma glucose and insulin levels, which is a reflection of ameliorated hepatic insulin sensitivity, as evidenced by a reduced AUC for the IPGTT." (PMID 36547081, 2022). "In the presence of elevated fasting insulin levels, the risk of hepatic steatosis was also significantly higher – OR 2.50 (p=0.006)." (PMID 36387906, 2022). "FGF21 is known to increase energy expenditure, fat utilization, and lipid excretion, causing weight loss, increased insulin sensitivity, decreased blood glucose and lipid levels, and the amelioration of hepatic steatosis." (PMID 36516179, 2022). "Such an impairment has previously been linked to adipose tissue inflammation, adipocyte apoptosis, hepatic steatosis and deteriorating systemic insulin sensitivity." (PMID 36158197, 2022). "Hepatic deletion of Pten results in overactive AKT, and thereby increases triglyceride (TG) synthesis and causes hepatic steatosis via insulin-induced lipogenesis." (PMID 36572670, 2022). "For this purpose, liver-specific PTEN knockout mice prove to be a useful model since these mice exhibit hepatic steatosis associated with hepatic IR, but also an improved skeletal muscle insulin sensitivity and a reduction and browning in white AT depots." (PMID 35409319, 2022). "Several studies have shown that mice fed a high-fat diet for several weeks develop NAFLD, but supplementation with betaine at the same time increased the SAMe level, prevented betaine deficiency and liver steatosis, and restored insulin sensitivity." (PMID 35893906, 2022). "Measures of hepatic steatosis and insulin sensitivity were improved in CD44-deficient mice on a C57BL/6J but not in the C3H/HeJ mice." (PMID 35410390, 2022). "Mice fed high fat diet (HFD) composed of 60% lard-based fat develop hepatic steatosis associated with oxidative stress, insulin resistance and inflammation." (PMID 36712976, 2022). "Blocking the IAA–AhR–IL-22 axis by treatment with neutralizing anti-IL-22 antibodies abrogates the protective effects of IDO1 deficiency against insulin sensitivity, liver steatosis, and intestinal permeability." (PMID 36144238, 2022). "The expression of regucalcin (Rgn) is stimulated by insulin in the liver, and decreased Rgn is associated with fatty liver disease in humans." (PMID 36359319, 2022). "The potent antisteatotic effects of krill oil, which have been observed in both the prevention and reversal of hepatic steatosis, were associated with improved insulin sensitivity in the liver and at the systemic level." (PMID 33572810, 2021). "Impairment of insulin action is associated with hepatic steatosis, which results in increased free fatty acid transport to the liver." (PMID 34944525, 2021). "In contrast, MED13 deficiency in skeletal muscle increased insulin sensitivity and protected mice against high-fat diet-induced hepatic steatosis." (PMID 33812059, 2021).
Hepatic steatosis (continued). "In conclusion, the beneficial effects of XOS on hepatic steatosis involved decreased adipose tissue inflammation and likely improved insulin signaling, which were further associated with fecal metabolites and GM." (PMID 33921370, 2021). "IR can also cause hepatic steatosis, and it has been proposed that hepatic steatosis further aggravates hepatic insulin resistance, creating a feedback loop between the two conditions." (PMID 33879188, 2021). "Overall, these results indicate that miR-22 deficiency improves glucose tolerance and insulin sensitivity and protects against liver steatosis under HFD conditions." (PMID 33664851, 2021). "Protection of BATiPLIN5 mice from HFD-induced hepatic steatosis was associated with increased hepatic insulin-stimulated AKT phosphorylation at serine 473 (WB left panel, quantification right panel)." (PMID 34083525, 2021). "Studies conducted on diet-induced obesity (DIO) mice showed that knocking out the Cnr2 gene encoding CB2R declined hepatic steatosis and improved peripheral insulin sensitivity." (PMID 33498537, 2021). "As a consequence, in animal models of NAFLD, the inhibition of ceramide synthesis is associated with decreased liver steatosis, cell injury, and insulin sensitivity." (PMID 34065331, 2021). "HuRLKO mice were susceptible to the development of HFD-induced hepatic steatosis, but also displayed improved systemic insulin sensitivity." (PMID 33664225, 2021). "We demonstrated positive associations of hepatic steatosis with markers of glucose metabolism including HbA1c, fasting glucose, 2-h glucose, fasting insulin, 2-h insulin, and HOMA-IR." (PMID 34168217, 2021). "Intrahepatic accumulation of fatty acids induces insulin resistance and endoplasmic reticulum stress, two factors previously implicated in the intracellular mechanism of lipid accumulation and hepatic steatosis development." (PMID 34768942, 2021). "A loss of muscle mass or fat accumulation is associated with a loss of insulin sensitivity, facilitating the progression of liver steatosis." (PMID 33898958, 2021). "The reduced liver steatosis was associated with reduced body weight in mice treated with insulin fused to apolipoprotein A-I." (PMID 33679386, 2020). "First of all, excess glucose and nutrients are stored as triglycerides in the liver and adipose tissue, causing organ-specific insulin resistance, hepatic steatosis and adipose enlargement at this stage." (PMID 32752112, 2020). "GLP-1R agonist-induced weight loss reduces hepatic steatosis and increases insulin sensitivity in GLP-1R-expressing hepatocytes." (PMID 32079069, 2020). "Our results demonstrate that hepatic steatosis diagnosed by ultrasound and TE in liver transplant recipients is associated with decreased serum adiponectin and increased serum leptin and insulin levels." (PMID 32728230, 2020). "Previously, we reported the protective effects of liraglutide on hepatic steatosis in β-cell-specific glucokinase-deficient mice with severe defects of insulin secretion." (PMID 33105604, 2020). "It is now clear that liver steatosis is closely linked to impaired insulin sensitivity and type 2 diabetes." (PMID 33186123, 2020). "Hepatic steatosis was most-strongly associated with blood glucose and insulin levels but negatively correlated with circulating fatty acids—indicating a more significant contribution from hepatic DNL than from adipose lipolysis." (PMID 32699301, 2020). "In contrast, a similar study using IRF9-deficient mice demonstrated that IRF9 promotes insulin sensitivity and attenuates inflammation and hepatic steatosis." (PMID 32660130, 2020). "Study has suggested that, in apparently healthy older adults, liver steatosis is associated with reduced hepatic insulin extraction and beta cell dysfunction after adjusting confounding factors of age, sex and alcohol consumption." (PMID 32528557, 2020).